ARRDC3 (arrestin domain containing 3)
Description:
Adapter protein that plays a role in regulating cell-surface expression of adrenergic receptors and probably also other G protein-coupled receptors. Plays a role in NEDD4-mediated ubiquitination and endocytosis af activated ADRB2 and subsequent ADRB2 degradation. May recruit NEDD4 to ADRB2. Alternatively, may function as adapter protein that does not play a major role in recruiting NEDD4 to ADRB2, but rather plays a role in a targeting ADRB2 to endosomes.
Synonyms: TLIMP; KIAA1376
Tractability: Antibody: UniProt places it where antibodies can reach, with high confidence; its Gene Ontology location is reachable by antibodies, with high confidence. PROTAC: ubiquitination databases record sites on it.
Gene: Protein-coding gene on chromosome 5 (91,368,631 to 91,383,317, reverse strand). Ensembl gene ENSG00000113369.
Subcellular location: Cytoplasm; Cell membrane; Lysosome; Endosome; Early endosome
Gene Ontology:
Molecular function: beta-3 adrenergic receptor binding; protein binding; molecular adaptor activity
Biological process: positive regulation of hippo signaling; positive regulation of ubiquitin-protein transferase activity; negative regulation of cold-induced thermogenesis
Cellular component: cytoplasm; early endosome; endosome; lysosome; plasma membrane
Genetic constraint (gnomAD): Loss-of-function variants: 7 observed, 40.49 expected, observed/expected ratio (o/e) 0.17, 90% interval 0.097 to 0.32. The upper end of that interval is the gene's LOEUF score, 0.32, which puts it in group 1 of 6, group 1 being the genes least tolerant of losing a copy. Missense variants: 340 observed, 483.25 expected, observed/expected ratio (o/e) 0.7, 90% interval 0.64 to 0.77. Synonymous variants: 140 observed, 172.42 expected, observed/expected ratio (o/e) 0.81, 90% interval 0.71 to 0.93.
Homologues: Orthologues: chimpanzee ARRDC3 (99% identical), macaque ARRDC3 (99% identical), pig ARRDC3 (99% identical), dog ARRDC3 (99% identical), rabbit ARRDC3 (99% identical), mouse Arrdc3 (98% identical), guinea pig ARRDC3 (96% identical), tropical clawed frog arrdc3 (90% identical), zebrafish arrdc3a (86% identical), rat Arrdc3 (79% identical), zebrafish arrdc3b (76% identical), Caenorhabditis elegans arrd-16 (25% identical), and 10 more. Paralogues in human: ARRDC2 (52% identical), ARRDC4 (51% identical), TXNIP (39% identical), ARRDC1 (22% identical), ARRDC5 (18% identical).
Diseases named in the same sentence as ARRDC3 in open-access papers:
ARRDC3 is named in the same sentence as 33 diseases in open-access papers, as found by Europe PMC text mining. Sharing a sentence is not in itself a finding about the gene and the disease. The quoted sentences say what the papers report.
breast cancer (20 papers, 2011 to 2025). A primary or metastatic malignant neoplasm involving the breast. "Similar effects of tryptase were also seen for a number of other genes implicated in breast cancer, as shown for ARRDC3 and Mir591." (PMID 41145489, 2025). "Suppression of ARRDC3 expression in breast cancer cells involving the epigenetic silencing caused by the deacetylases directly impacted signaling to downstream TFs." (PMID 33802957, 2021). "ARRDC3 is associated with inflammation, cellular invasion, etc., which promotes H. pylori-associated gastritis by regulating protease-activated receptor 1 and inhibits invasive metastasis of breast cancer cells by regulating G protein-coupled receptor lysosomes." (PMID 37821869, 2023). "ARRDC3 has recently been reported to inhibit EMT in triple knockout breast cancer and has tumor suppressing properties." (PMID 40495676, 2025). "ARRDC3 is a member of the arrestin superfamily and has been shown to suppress metastatic breast cancer by inducing ubiquitination and degradation of the β2-adrenergic receptor and the β4-integrin." (PMID 36904165, 2023). "ARRDC3 has been shown to be involved in regulating the progression of many cancers, like colorectal cancer and breast cancer." (PMID 37215052, 2023). "Arrdc3 has been well-studied in breast cancer, and it inhibits proliferation of human breast cancer cells." (PMID 36417410, 2022). "ARRDC3 was demonstrated to inhibit PAR1-dependent Hippo signaling in breast cancer cells in a novel, PAR1-degradation-independent manner, by directly interacting with TAZ and inhibiting its activity." (PMID 35563378, 2022). "ARRDC3 can also reduce the metastatic potential of breast cancer cell-derived integrin β4 + EVs, which are mainly detectable from supernatants of TNBC by reducing integrin β4 levels in EVs." (PMID 34439865, 2021). "It has previously been shown that PAR1, a GPCR, is regulated via ARRDC3-mediated lysosomal degradation in breast carcinoma." (PMID 32634127, 2020). "ARRDC3 levels were very low to undetectable in mesenchymal subtype (Basal B) of TNBC cell lines in comparison to luminal subtype of breast cancer cell lines and epithelial subtype (Basal A) of TNBC cell lines." (PMID 31295851, 2019). "To further define relationship between ARRDC3 levels and EMT phenotypes, we selected a panel of breast cancer cell lines with different ARRDC3 levels." (PMID 31295851, 2019). "Metastasis and tumor-suppressing roles of ARRDC3 in multiple cancer models including breast cancer have been demonstrated recently." (PMID 31295851, 2019). "Overall, our studies indicate the importance of ARRDC3 in regulating metastatic potentials of breast cancer cell-derived EVs." (PMID 30545011, 2018). "Inhibition of ITG β4 recycling by ARRDC3 also has implications in regulating tumorigenic and invasive potential of breast cancer cell-derived EVs by reducing the levels of ITG β4+ EVs that confer invasive potentials to non-invasive recipient cells." (PMID 30545011, 2018). "ARRDC3 reduces the metastatic potentials of breast cancer cell-derived EVs by reducing ITG β4 levels in EVs." (PMID 30545011, 2018). "A majority of TNBC cell lines belong to ARRDC3 low expression group (0.003–1.2 scale) whereas luminal subtype of breast cancer cell lines belong to ARRDC3 high expression group (3.4–12.1)." (PMID 28881784, 2017). "A negative regulation of β2 AR and ITG β4, whose roles in breast cancer progression are established, by ARRDC3 indicates its role as a potential metastatic suppressor." (PMID 28881784, 2017). "We found that ARRDC3 expression is lower in TNBC cell lines than those of luminal breast cancer cell lines, and inversely correlated with IC50s of selinexor." (PMID 28881784, 2017). "Breast cancer tissue arrays were stained with anti-ARRDC3, anti-XPO1, and anti-ITG β4 antibodies for immunohistochemistry analysis." (PMID 28881784, 2017).
breast cancer (continued). "Conversely, the over-expression of ARRDC3 in MDA-MB-231 basal-like breast cancer cells represses cell proliferation, migration, invasion, growth in soft agar, and tumorigenicity following injection in nude mice." (PMID 27534529, 2016). "Expression of ARRDC3 is down-regulated in breast cancers compared to normal tissue, and expression decreases with tumor grade, metastases, and recurrences." (PMID 27534529, 2016). "Up-regulation of ARRDC3 would be a beneficial effect of SINE compound treatment as it was shown that its overexpression represses breast cancer cell proliferation and does so by negatively regulating beta-4 integrin." (PMID 26573568, 2015). "For instance, the product of target gene ARRDC3 can bind and degrade the ITGβ4 protein, which affects the proliferation, migration and invasion of breast cancer cells in vitro." (PMID 21799901, 2011). "Furthermore, ARRDC3 overexpression increases apoptosis in breast cancer cells, whereas inhibition significantly inhibits apoptosis." (PMID 36417410, 2022). "Indeed, restoration of ARRDC3 synthesis in breast cancer cells improved ligand-induced degradation of PAR1, inhibited its persistent activation and thus attenuated PAR1-dependent cancer cell invasiveness." (PMID 35563378, 2022). "It is possible that reversal of EMT phenotypes is linked to sensitization of mesenchymal subtype of TNBC cells to DNA damaging agents such as 5-FU whereas non-mesenchymal breast cancer cells are less susceptible by increasing ARRDC3 or miR-200b expression." (PMID 31295851, 2019). "Based on the heterogenous nature of TNBC, it remains to be determined whether therapeutic targeting of ARRDC3/miR-200b pathway is effective in breast cancer in general, or more effective on specific subtypes of TNBC." (PMID 31295851, 2019). "In addition, ARRDC3, which is a tumor suppressor and involved in integrin trafficking, was upregulated in breast cancer, whereas FN1 was downregulated after liprin-α1 knockdown." (PMID 30005669, 2018). "Moreover, ARRDC3 localizes to a gene cluster on chromosome 5 deleted in 17% of basal-like breast cancers compared to 0% deletion in luminal breast cancers." (PMID 29954076, 2018). "ARRDC3 expression is low or absent in the highly aggressive basal-like breast cancer, and associated with tumor grade, metastasis and recurrence." (PMID 29954076, 2018). "In mammary tumor cells, repression of ARRDC3 enhanced the proliferation and migration." (PMID 27699500, 2017). "The outcome further supports our hypothesis that selinexor works more efficiently in breast cancers with down-regulated ARRDC3 as restoration of ARRDC3 expression is an important therapeutic mechanism of this drug." (PMID 28881784, 2017). "To test this hypothesis, we measured the steady state protein levels of ARRDC3 in 12 breast cancer cell lines with different subtypes (4 luminal and 8 TNBC subtypes)." (PMID 28881784, 2017). "Besides, ARRDC3 took part in the regulation of breast cancer." (PMID 37215052, 2023). "In addition, ARRDC3 is epigenetically regulated in breast cancer cells." (PMID 36417410, 2022). "ARRDC3 is known to participate in the negative regulation of the PAR1 receptor, which is overproduced in breast cancer cells, and aberrations in its signaling, for instance, due to dysregulation of lysosomal trafficking, influence metastasis." (PMID 35563378, 2022). "In contrast to ARRDC3, ALIX expression in invasive versus non-invasive breast cancer is variable and is consistent with human cancers that exhibit both upregulated and downregulated ALIX expression." (PMID 29954076, 2018). "For the next common core signaling pathway, the receptor ERBB2, which was mutated in breast cancer, received microenvironment factor CCL28 to activate TF BRCA1 through signaling transduction proteins CDC42 and ARRDC3 in TNBC and non-TNBC." (PMID 33802957, 2021).
breast cancer (continued). "Our data that miR-200b effectively reduces proliferation of TNBC cell line (MDA-MB-231), but not luminal subtype breast cancer cells (MCF-7) suggest that targeting ARRDC3/miR-200b pathway can be more effective in TNBC." (PMID 31295851, 2019). "In addition, the role of ARRDC3 in sorting of ITG β4 into EVs and its implication in the metastatic potentials of breast cancer cell-derived EVs was assessed." (PMID 30545011, 2018). "In the current study, we tested the hypothesis that a metastastic suppressor, ARRDC3 (arrestin domain-containing 3) is a major regulator in determining efficiency of ITG β4 recycling and its sorting into breast cancer cell-derived EVs." (PMID 30545011, 2018). "Importantly, the sensitivity of breast cancer cells to SINE compounds may depend not only on ARRDC3 protein levels, but also on the availability of ARRDC3 downstream substrates and their phosphorylation status as ARRDC3 only interacts with phosphorylated form of their substrates." (PMID 28881784, 2017).
Obesity (14 papers, 2012 to 2025). Accumulation of substantial excess body fat. "Mutations or dysregulation of ARRDC3 can affect these pathways and have been linked to various disorders, including obesity, cancer, and metabolic syndromes." (PMID 40491568, 2025). "In a mouse model, loss of ARRDC3 expression protects against obesity and increases energy use by improving the thermogenesis of both brown and white fat tissues." (PMID 30691068, 2019). "The arrestin domain containing protein Arrdc3 is a regulator of obesity in mice and also appears linked to obesity in humans." (PMID 28291835, 2017). "Animal models such as the Arrdc3 deficient mice have validated the role of ARRDC3 in metabolism by being resistant to obesity in a dosage dependent manner (both genders, but with greater impact on males than females)." (PMID 25825681, 2015). "The ARRDC3 protein is also linked to adipocyte function and human obesity." (PMID 37451484, 2023). "Higher ARRDC3 expression is associated with visceral adipose tissue and obesity in males." (PMID 25825681, 2015). "Interestingly, some of this regulation is gender specific, with increased expression of ARRDC3 in males from Icelandic populations linked to obesity and increased expression of ARRDC3 in omental adipose correlated with obesity in males (and references therein)." (PMID 30691068, 2019). "Another potential candidate gene is the ARRDC3, a member of the arrestin superfamily, which is probably involved in obesity, growth, and adipose tissue development." (PMID 40452020, 2025). "Relevant miRNA-to-mRNA regulatory networks were also predicted (i.e., mir15b to ARRDC3; mir-7142-3p to METTL21C), and linked to lipolysis, obesity, myogenesis, and protein degradation." (PMID 37141193, 2023). "Future mechanistic studies exploring the relationship between miR-10b-5p, ARRDC3 as it relates to obesity, and type 2 diabetes are warranted." (PMID 34041258, 2021). "Although there are no mechanistic studies to date examining the direct role of miR-10b-5p on ARRDC3 as it relates to obesity or subsequent diseases, to date, one study explored the association between miR-10b-5p in children with obesity." (PMID 34041258, 2021). "It has been suggested that ARRDC3 is critically involved in obesity and energy expenditure, owing to its function in fat pad development and role in thermoregulation." (PMID 34041258, 2021). "Arrestin domain containing 3 (ARRDC3) represents a newly discovered α-arrestin involved in obesity, inflammation, and cancer." (PMID 32634127, 2020). "Arrdc3-null mice appeared resistant to obesity through increased energy expenditure and increased Ucp1 expression in white adipose tissue." (PMID 28291835, 2017). "Previously we identified arrestin domain-containing 3 protein (Arrdc3) as a regulator of obesity through the combination of human linkage data, human expression data, and mouse genetic studies." (PMID 28291835, 2017). "For example, ARRDC3, up-regulated in the less efficient group, plays a role in the regulation of metabolism and obesity in humans and mice." (PMID 28004777, 2016). "Patwari and colleagues recently reported metabolic studies showing that Arrdc3 knockouts are resistant to age-induced obesity in C57/BL6 mice (using a separate insertion of the same gene trap vector into the same intron)." (PMID 23236378, 2012). "However, this adipocyte effect is insufficient to generate the obesity-resistant phenotype of mice with ubiquitous deletion of Arrdc3, indicating a likely role for Arrdc3 in cells other than adipocytes." (PMID 28291835, 2017). "Genome wide linkage for human obesity identified a linkage peak on chromosome 5, and positional cloning identified ARRDC3 associated with higher BMI in males but not in females." (PMID 25825681, 2015). "Others recently reported that Arrdc3 knockout mice are lean and resistant to obesity." (PMID 23236378, 2012).
Obesity (continued). "Arrdc3’s involvement in β2-adrenergic receptor action is a finding of particular significance as the β-adrenergic receptor is a principal activator and recruiter of brown/beige adipocytes and has been the focus of multiple pharmacological obesity interventions." (PMID 28291835, 2017).
prostate carcinoma (5 papers, 2018 to 2024). A carcinoma that arises from epithelial cells of the prostate gland. "A better characterized member of this family, ARRDC3, is a breast and prostate cancer suppressor; lower expression of ARRDC3 was significantly associated with high aggressiveness and metastasis in prostate cancer cells." (PMID 33175867, 2020). "Lastly, rs2939244 results in the variation of the androgen receptor-binding site gene ARRDC3 which affects prostate cancer specific mortality." (PMID 29560112, 2018). "Interestingly, ARRDC3 has been reported to act as tumor suppressor in different types of cancers, such as breast, colorectal and prostate cancer." (PMID 34439361, 2021).
triple-negative breast carcinoma (3 papers, 2017 to 2022). An invasive breast carcinoma which is negative for expression of estrogen receptor (ER), progesterone receptor (PR), and human epidermal growth factor receptor 2 (HER2). "Our previous studies demonstrated the importance of arrestin domain containing 3 (ARRDC3), a metastasis suppressor, in inhibiting invasive and metastatic potential of triple negative breast cancer (TNBC) in vitro and in vivo." (PMID 31295851, 2019). "Our previous studies demonstrated that expression of ARRDC3 is epigentically silenced in Triple Negative Breast Cancer (TNBC) cells, and the forced expression of ARRDC3 significantly reduced the invasive potential of TNBC cells." (PMID 28881784, 2017).
cardiac hypertrophy (2 papers, 2022). "Also the following tachycardia-specific miR-1183-regulated targets showed a cardiovascular association: the gene NEU3 with cardiac fibrosis and CHD, ZNRD1 with CHD, TRIM16 with cardiac hypertrophy, BIRC3 with ischemic preconditioning, ARRDC3 with cardiac hypertrophy, and MTAP with ischemic stroke." (PMID 35805966, 2022).
colorectal cancer (2 papers, 2023 to 2025). A primary or metastatic malignant neoplasm that affects the colon or rectum. "Upregulation of ARRDC3 suppresses colorectal cancer progression by destabilizing the oncoprotein YAP." (PMID 40491568, 2025).
gastritis (2 papers, 2020 to 2023). Inflammation of the stomach. "Collectively, these data point out a potentially novel proinflammation role of ARRDC3 in the GECs during H. pylori–associated gastritis." (PMID 32634127, 2020). "As cagA is strongly associated with the development of gastritis, we next investigated the relationship between cagA and ARRDC3 and found that ARRDC3 expression in cagA-positive patients was significantly higher than that in cagA-negative individuals." (PMID 32634127, 2020). "Here, we demonstrate a proinflammation role of ARRDC3 in Helicobacter pylori–associated gastritis." (PMID 32634127, 2020). "Efforts to inhibit this ARRDC3-dependent pathway may provide valuable strategies in treating of H. pylori–associated gastritis." (PMID 32634127, 2020). "In this study, we demonstrate that H. pylori infection led to an increase of ARRDC3 in GECs, which may be important in H. pylori–induced gastritis through degradation of PAR1." (PMID 32634127, 2020).